TMZR1 (temozolomide resistance associated STAT3 regulator 1)
Gene: Long non-coding RNA gene on chromosome 17 (42,409,892 to 42,411,209, reverse strand). Ensembl gene ENSG00000289579.
Diseases named in the same sentence as TMZR1 in open-access papers:
TMZR1 is named in the same sentence as 2 diseases in open-access papers, as found by Europe PMC text mining. Sharing a sentence is not in itself a finding about the gene and the disease. The quoted sentences say what the papers report.
glioma (1 paper, 2025). A benign or malignant brain and spinal cord tumor that arises from glial cells (astrocytes, oligodendrocytes, ependymal cells). "Collectively, the studies on TMZR1-eRNA and LINC02454 underscore that eRNAs are key modulators of chemotherapeutic response in glioma." (PMID 41154382, 2025). "Several eRNAs, including TMZR1-eRNA and LINC02454, influence sensitivity to temozolomide (the main chemotherapeutic agent for glioma) by modulating STAT3 and DDR1 signaling." (PMID 41154382, 2025).
TMZR1 also shares sentences with these, for which no sentence is quoted: glioblastoma (1 paper).